PLA2G7 (phospholipase A2 group VII)
Diseases named in the same sentence as PLA2G7 in open-access papers (continued):
Sharing a sentence is not in itself a finding about the gene and the disease.
cardiovascular disease (105 papers, 2009 to 2026). "Adipose tissue macrophages were found to have substantiallyreduced PLA2G7 expression, which is of particular interest given previous researchimplicating PLA2G7 as an independent cardiovascular disease risk marker." (PMID 35497092, 2022). "Phospholipase A2, group VII (PLA2G7) gene encodes a kind of secreted enzyme, and patients with high PLA2G7 expression was found to have an increased risk of cardiovascular diseases." (PMID 27461004, 2016). "Accordingly, PLA2G7 mass and activity have been associated with an increased risk of cardiovascular diseases." (PMID 22202492, 2011). "PLA2G7 inhibition represents a promising therapeutic strategy for a plethora of indications, including cardiovascular diseases, aging, and cancers." (PMID 40136470, 2025). "Recently, PLA2G7 has emerged as a promising target for therapeutic intervention due to its multifaceted roles in various pathological processes, particularly in cardiovascular diseases, aging, and cancers." (PMID 40136470, 2025). "Overall, PLA2G7 has been extensivelyexplored in coronary and cardiovascular disease due to its upregulation in activatedmacrophages and its potential role in cardiovascular aging." (PMID 35497092, 2022). "As reported, phospholipase A2 group VII (PLA2G7), a well‐known cardiovascular disease biomarker, was predominantly expressed by proinflammatory macrophages in lungs at the early stage." (PMID 34766152, 2021). "In contrast to cancer, the role and therapeutic potential of PLA2G7 has been under intensive research in the area of cardiovascular diseases." (PMID 22202492, 2011). "Furthermore, in cardiovascular diseases widely used and clinically well tolerated lipid-lowering statins are known to exert part of their beneficial effects via PLA2G7 inhibition." (PMID 22202492, 2011). "One of the main challenges in targeting PLA2G7 with small-molecule inhibitors like darapladib is their short half-life (~30 h), which necessitates frequent dosing and may limit their long-term efficacy in cardiovascular disease and cancer therapy." (PMID 40136470, 2025). "As for some studies published on PLA2G7 and darapladib in the context of cardiovascular diseases, the current study does not highlight any crucial effect of PLA2G7 on CCx pathogenesis." (PMID 34427055, 2021).
cancer (34 papers, 2011 to 2026). A tumor composed of atypical neoplastic, often pleomorphic cells that invade other tissues. "The phospholipase A2 Group 7 (PLA2G7), which is mainly secreted by macrophages, interacts with oxidized low-density lipoprotein (oxLDL) and associates with several vascular diseases and cancers." (PMID 40136470, 2025). "Elevated PLA2G7 activity has been associated with increased tumor cell migration, invasion, and metastasis in various cancer types." (PMID 40136470, 2025). "Through this strategy, we identified phospholipase A2 group VII (PLA2G7) as a novel biomarker of interest associated with this cancer type." (PMID 34404374, 2021). "Recent studies have also identified PLA2G7 as a pan-cancer diagnostic and prognostic marker." (PMID 40136470, 2025). "Interestingly, the PLA2G7 gene, which encodes Lp-PLA2, plays a crucial role in the oncogenesis of various human cancers, including those within the CNS." (PMID 40869314, 2025). "The majority of the genes synergistically upregulated by inhibition of both PD-L1 and TGF-β were associated with metabolic pathways (Nqo1, Hmgsc1, Sult1a1, Pla2g7, Ugt1A5, Ugt2B5, Abcb1a), that enhance cancer cell proliferation, invasion, and metastasis (Fig-6D)." (PMID 38516270, 2024). "Importantly, different types of cancers harbor different levels of PLA2G7 mutations; thus, the effects of PLA2G7 mutations should be taken into consideration when determining the role of Lp‐PLA2 in the pathogenesis of certain cancers." (PMID 31140638, 2020). "Given PLA2G7’s role in promoting cancer cell migration, the anti-migratory effects observed with 1H8 IgG and 1H8 IgG-1A9 in our study are particularly encouraging." (PMID 40136470, 2025). "On the one hand, some studies have shown that high level of PLA2G7 was positively correlated with aggressiveness in cancer." (PMID 37704909, 2023). "Here, we identified the phospholipase PLA2G7 as a consistent marker of CCx in both well‐established mouse models of CCx and cachectic cancer patients with various tumour entities." (PMID 34427055, 2021). "The early increase in circulating PLA2G7 levels in pre‐cachectic mice supports future prospective studies to assess its potential as biomarker for cancer patients." (PMID 34427055, 2021). "Pla2g7 is a cancer-selective biomarker; silencing of Pla2g7 is an antiproliferative and proapoptotic therapeutic approach in cancer treatment." (PMID 30275866, 2018). "Selected targets were confirmed by immunohistochemistry: NPY and PLA2G7 (up-regulated in ERG+ cancers), and AZGP1 and TFF3 (down-regulated in ERG+ cancers)." (PMID 23390522, 2013). "However, further studies are needed to fully elucidate the mechanisms by which PLA2G7 contributes to cancer progression and to optimize the therapeutic efficacy of these mAbs." (PMID 40136470, 2025). "Given that PLA2G7 has been reported to increase cancer cell migration, and PLA2G7 knockdown by siRNA led to reduced cancer cell migration, we next evaluated the inhibition of PLA2G7-mediated cell migration by our anti-PLA2G7 antibodies on both HCT116 and HT29 cells." (PMID 40136470, 2025). "However, the application of PLA2G7 inhibition in cancer therapy is still in its early stages, and there are concerns about the ability of inhibitors to effectively target and modulate cancer-associated PLA2G7 activity in vivo." (PMID 40136470, 2025). "Overall, our work highlights PLA2G7 as a signature of cachexia‐inducing cancer cell lines." (PMID 34427055, 2021). "To determine the relative contribution of PLA2G7 to tissue wasting in cancer, we generated C26 cells with a stable knock‐down for Pla2g7 (C26‐shPla2g7), through the transfection of a plasmid expressing a shRNA against Pla2g7 and subsequent selection of transfected cells." (PMID 34427055, 2021).
cancer (continued). "Future longitudinal prospective studies on larger cohorts of cancer patients, controlled for intervention strategies and co‐morbidities, will be necessary to confirm the predictive potential of PLA2G7 in combination with other established markers for CCx diagnosis." (PMID 34427055, 2021). "To determine whether PLA2G7 is also a marker of CCx in humans, we measured its circulating levels in different cohorts of cancer patients with different tumour entities and degrees of body weight loss." (PMID 34427055, 2021). "High expression and secretion of PLA2G7 were hallmarks of cachexia‐inducing cancer cell lines." (PMID 34427055, 2021). "Interestingly, PLA2G7 protein and activity levels were more efficient to discriminate between cachectic and non‐cachectic cancer patients than IL‐6 and GDF‐15, two other factors proposed as biomarkers for CCx diagnosis." (PMID 34427055, 2021). "The expression of PLA2G7 in THP-1 cells or these cancer cells was examined." (PMID 27487154, 2016). "Furthermore, investigations have also found that PLA2G7 is involved in the development of multiple tumors and the PLA2G7 inhibitor darapladib plays a significant inhibitory role in a variety of tumors by sensitizing cancer cells to ferroptosis." (PMID 40169540, 2025). "The L3MBTL3, PLA2G7, KIAA1614, and C3orf33 genes were implicated in DNA repair, cell proliferation, apoptosis, and the cell cycle, and may be involved in the development of cancers." (PMID 39839768, 2024). "Therefore, the induction of PLA2G7 expression in TAMs by cancer cells could be an important factor in tumor-promoting function of TAMs in various cancers." (PMID 27487154, 2016). "PLA2G7, on the other hand, was found to be induced at 24 hrs post co-culture and its expression was sustained thereafter The majority of these cancer-promoting factors were also found to be expressed mainly in the THP-1 cells after co-culture with the NPC cells." (PMID 27487154, 2016). "However, PLA2G7 positivity is not restricted to ERG positive cancer cells since other oncogenic mutations have been recently shown to induce PLA2G7 expression." (PMID 22202492, 2011). "Here, we identified the phospholipase A2 group VII (PLA2G7) as a tumour‐derived and host‐derived factor specifically increased in both well‐established mouse models of CCx and cachectic cancer patients." (PMID 34427055, 2021). "After demonstrating the functional impact of PLA2G7 and its protein PAF-AH on cancer progression, we aimed to validate how PLA2G7 affects the Wnt/β-catenin signaling pathway." (PMID 34206491, 2021). "Overexpression of PLA2G7 as a member of arachidonic acid and prostaglandin pathway in PCa, specifically in ERG positive cancers, has been reported." (PMID 27196083, 2016). "Accordingly, we recently reported reduced plasma levels of various LPC species in different mouse models of CCx as well as cachectic cancer patients, suggesting that PLA2G7 is not crucial for LPC turnover in CCx." (PMID 34427055, 2021). "Importantly, we observed that several other cancer-promoting genes including CTGF, PLAU and PLA2G7 were induced in macrophages during macrophage-NPC interaction." (PMID 27487154, 2016). "As for TDRD1 and PLA2G7, progression-associated overexpression of CACNA1D may be largely independent of ERG-status in these cancers, and apparently occurs also in ERG-negative cancers." (PMID 27196083, 2016). "All of our eight candidate genes showed statistically significantly different expression between normal/benign prostate and malignant PCa sample groups, low versus high Gleason grade tumors (PLA2G7), PSA relapse versus no relapse (SPON2), and low versus high TNM stages (CACNA1D and DLX1)." (PMID 27196083, 2016).
tumor (26 papers, 2010 to 2025). "ANKRD66 is associated with enhanced cell proliferation in tumor cells, whereas PLA2G7 catalyzes phospholipid hydrolysis to produce arachidonic acid, participating in inflammatory signaling and lipid metabolism." (PMID 41246275, 2025). "Prior research indicates that PLA2G7 is a tumor-associated macrophage-derived factor that plays a key role in the regulation of tumor cell migration." (PMID 34404374, 2021). "We therefore assessed the therapeutic potential of the specific PLA2G7 inhibitor darapladib in preventing CCx development in pre‐cachectic tumour‐bearing mice (i.e. before onset of body weight loss)." (PMID 34427055, 2021). "Circulating PLA2G7 activity was increased in different mouse models of CCx with various tumour entities and was associated with the severity of body wasting." (PMID 34427055, 2021). "Overall, these data show that increased circulating PLA2G7 levels are a hallmark of CCx in mice representing different tumour entities." (PMID 34427055, 2021). "PLA2G7 was also found to be closely linked to tumor microenvironmental composition such that DLBCL patients expressing higher levels of this gene exhibited high local monocyte and gamma delta T cell levels." (PMID 34404374, 2021). "A recent study showed that PLA2G7 highly expressed in HCC tumor tissue compared with normal tissue may act as a diagnostic marker of HCC." (PMID 40075616, 2025). "Lipoprotein-associated phospholipase A2 (PLA2G7) silencing was recently reported that could as a novel therapy involving in anti-proliferative, anti-migratory and pro-apoptotic in tumor cells." (PMID 34852326, 2021). "The data generated in the present study further suggest that PLA2G7 expression may be associated with DLBCL tumor stromal and immune scores." (PMID 34404374, 2021). "Furthermore, PLA2G7 activity has also been linked to enhanced tumor cell migration and invasion." (PMID 40136470, 2025). "PLA2G7 not only directly promotes tumor growth and migration, but also contributes to the immunosuppressive nature of the tumor microenvironment." (PMID 40136470, 2025). "Results indicated that PLA2G7 depletion reduced MBT-2 tumor growth, and the combination of PLA2G7 depletion with CTLA4 blockade significantly improved the inhibitory effect on tumor burden." (PMID 40169540, 2025). "Genetic PLA2G7 knock‐down in C26 tumours only partially reduced plasma PLA2G7 levels, suggesting that the host is also an important contributor." (PMID 34427055, 2021). "Genetic PLA2G7 knock‐down in tumours and pharmacological treatment using the well‐studied PLA2G7 inhibitor darapladib were performed to assess its implication in the pathogenesis of CCx in C26 tumour‐bearing mice." (PMID 34427055, 2021). "High circulating PLA2G7 levels are a consistent marker of CCx in both mice and patients carrying diverse tumour entities." (PMID 34427055, 2021). "Together, these data provide clear evidence in support of a model wherein PLA2G7 plays an oncogenic role in DLBCL by inhibiting tumor cell apoptotic death while simultaneously enhancing proliferation and migration." (PMID 34404374, 2021). "Even more interestingly, circulating PLA2G7 levels were able to predict the time of CCx development in C26 tumour‐bearing mice independently of their tumour size." (PMID 34427055, 2021). "These analyses revealed that PLA2G7 expression was significantly elevated in 17 tumor types, including DLBCL, relative to corresponding normal tissue controls." (PMID 34404374, 2021). "We have also identified one of these macrophage-derived factor, phospholipase A2 Group 7 (PLA2G7), to be important in regulating tumor cell migration and a novel tumor-promoting factor in NPC." (PMID 27487154, 2016). "Tumor cell and TAMs express multiple genes for secreted phospholipases, with PLA2G7, preferentially expressed by TAMs, as the major subtype." (PMID 27215396, 2016).
tumor (continued). "Additionally, 1H8 IgG and its derivative bispecific antibody exhibited the ability to block PLA2G7-mediated tumor cell migration." (PMID 40136470, 2025). "Notably, combining PLA2G7 depletion with CTLA-4 blockade significantly improved the suppression of tumor burden and mouse survival rates." (PMID 40169540, 2025). "Moreover, our anti-PLA2G7 mAbs represent promising fully human PLA2G7 enzymatic blockade antibodies with the potential to enhance both anti-tumor and anti-aging responses." (PMID 40136470, 2025). "PLA2G7 inhibition by siRNA could alter the immunosuppressive tumor microenvironment, potentially enhancing the efficacy of T cell immune checkpoint blockade antibodies." (PMID 40136470, 2025). "Together, our data suggest that PLA2G7 may function as a driver of the proliferation, migration, and survival of tumor cells and a regulator of immune cell infiltration within the DLBCL tumor microenvironment." (PMID 34404374, 2021). "Knockdown of PLA2G7 suppressed the ability of these DLBCL tumor cells to migrate and form colonies." (PMID 34404374, 2021). "In the GTex and TCGA databases, PLA2G7 was found to be upregulated in 17 different tumor types." (PMID 34404374, 2021). "We then conducted a qRT-PCR-based comparison of PLA2G7 mRNA expression in DLBCL patient tumor tissues and benign lymphadenitis patient tissues, leading us to confirm that this gene is highly expressed in DLBCL tissues (mean = 14.95, 95% confidence interval = 4.661–25.23)." (PMID 34404374, 2021). "In vivo, once tumours were palpable, C26 tumour‐bearing mice were treated once daily either with a vehicle solution or darapladib at a dose that efficiently inhibited circulating PLA2G7 activity over 24 h." (PMID 34427055, 2021). "Increased tumor-infiltrating monocyte numbers may thus be responsible for the relationship between high PLA2G7 expression and poor DLBCL patient outcomes." (PMID 34404374, 2021). "Next, we determined whether circulating PLA2G7 levels were altered in different well‐established mouse models of CCx with various tumour entities." (PMID 34427055, 2021). "In vivo, Pla2g7 expression was also higher in C26 tumours than in MC38 tumours." (PMID 34427055, 2021). "Our results indicated that GZZSZTW significantly increased the expression levels of multiple genes involved in promoting cell proliferation, most of which are highly expressed in tumor cells, such as Tnfaip2, Chi3l1, Tnf, Pfkfb3, Sox8, Jag1, Mafb, Pla2g7, Hnrnpa1, and E2f3." (PMID 30275866, 2018). "Novel targets such as phospholipase A2 group VII (PLA2G7) that may contribute to tumor progression were also identified from our screen." (PMID 27487154, 2016). "In addition, absence of PLA2G7 in APCmin/+ mice resulted in reduced intestinal tumorigenesis, providing further evidence of tumor-promoting function of PLA2G7 in CRC." (PMID 27487154, 2016). "Further studies to characterize the role of PLA2G7 in tumor metastasis may help determine its potential as a therapeutic target in NPC." (PMID 27487154, 2016). "Moreover, recent studies have found that PLA2G7 also plays an important role in tumor immunity." (PMID 40169540, 2025). "Importantly, this study highlights the predictive potential of PLA2G7 in different tumour entities and may pave the way for future studies on PLA2G7 as biomarker of CCx." (PMID 34427055, 2021). "Thus, increased activation of the Wnt signaling could be responsible for tumor progression under PLA2G7 knockdown." (PMID 34206491, 2021). "Meanwhile, results from syngeneic mouse models indicated that PLA2G7 suppression and anti-CTLA4 therapy have synergistic effects on tumor burden and mouse survival." (PMID 40169540, 2025).